SNORD116-7 (small nucleolar RNA, C/D box 116-7)
Synonyms: HBII-85-7
Gene: Small nucleolar RNA gene on chromosome 15 (25,067,788 to 25,067,882, forward strand). Ensembl gene ENSG00000207133.
Gene Ontology:
Biological process: RNA processing
Cellular component: nucleolus
Homologues: Orthologues: macaque SNORD116 (97% identical), rabbit SNORD116 (89% identical), rabbit SNORD116 (88% identical), rabbit SNORD116 (87% identical), rabbit SNORD116 (86% identical), rabbit SNORD116 (83% identical), rabbit SNORD116 (78% identical), rabbit SNORD116 (77% identical). Paralogues in human: SNORD116-5 (100% identical), SNORD116-3 (99% identical), SNORD116-9 (99% identical), SNORD116-8 (97% identical), SNORD116-1 (96% identical), SNORD116-4 (96% identical), SNORD116-2 (95% identical), SNORD116-6 (94% identical), SNORD116-14 (86% identical), SNORD116-15 (86% identical), SNORD116-17 (85% identical), SNORD116-19 (85% identical), and 20 more.